IL10 (interleukin 10)
Diseases named in the same sentence as IL10 in open-access papers (continued):
Sharing a sentence is not in itself a finding about the gene and the disease.
HIV-1 infection (53 papers, 2008 to 2025). The type species of lentivirus and the etiologic agent of acquired immunodeficiency syndrome (AIDS). "Inflammation is associated with untreated HIV-1 infection, and high baseline levels of IL-6, IL-10, and TNF-α are associated with increased risks of AIDS-defining events." (PMID 34983415, 2022). "M(IL-10) macrophages are highly susceptible not only to Mtb infection, but also to HIV-1 infection and spread." (PMID 32223897, 2020). "In HIV-1 infection, single nucleotide polymorphism (SNP) of the IL-10 promoter (-592A) has been implicated in increased susceptibility to HIV-1 infection and AIDS progression." (PMID 31438973, 2019). "Several studies show that alleles associated with low serum levels of IL-10 are linked to increased susceptibility to HIV-1 infection and accelerated progression to AIDS, particularly in later stages of the disease." (PMID 25802474, 2015). "In a multi-cohort analysis, European Americans carrying the A allele at the −592 position (rs1800872) of IL10 promoter were at increased risk for HIV-1 infection (OR = 1.75, p = 0.03)." (PMID 20976276, 2010). "TB-induced M(IL-10) macrophages are highly susceptible to HIV-1 infection and spread." (PMID 32223897, 2020). "Interestingly, this miRNA was reported to be down-modulated also by murine Cytomegalovirus and HIV-1 infection, where it was associated with an increase of anti-inflammatory IL-10, thus providing viruses with an important immune escape mechanism." (PMID 29163428, 2017). "Persistent HIV-1 infection is associated with abnormal hyper-activation of the immune system and the expression of multiple immunosuppressive factors including interleukin-10 (IL-10), programmed death ligand-1 (PD-L1), programmed death receptor 1 (PD-1) and indoleamine 2,3 dioxygenase (IDO)." (PMID 26090662, 2015). "Individual cytokines (IL-10 and IL-13) correlated with a decreased risk of HIV-1 infection." (PMID 24932411, 2014). "The IL10 gene has been implicated in HIV-1 infection and pathogenesis in numerous studies." (PMID 20976276, 2010). "Our study suggests that variants within the IL10 gene pathway might influence various immunological and virological outcomes of HIV-1 infection and immunological response to HAART in African Americans." (PMID 20976276, 2010). "In African Americans, variants in IL10 and related genes might influence multiple outcomes of HIV-1 infection, especially immunological response to HAART." (PMID 20976276, 2010). "Interestingly, we observed a modest, albeit significant, induction of Siglec-1 expression in cells treated with interleukin 10 (IL-10), a cytokine we have previously shown to be abundant in cmMTB and that renders macrophages highly susceptible to HIV-1 infection." (PMID 32223897, 2020). "In human immunodeficiency virus 1 (HIV-1) infection, IL-10 is produced and is considered an important pathway by which HIV can induce immunodeficiency." (PMID 39943198, 2025). "It has been reported that HIV-1 infection increases the level of IL-10 and suppression of IL-10 improves the function of T cells in HIV-1 patients." (PMID 39119118, 2024). "For example, IL-1α, IL-10, CCL2, LMNA, and VCAM1, the target genes identified in this study, have been reported to be associated with HIV-1 infection and pathogenesis." (PMID 38110484, 2023). "Plasma IL-10 levels have been found to be higher in subjects with HIV-1 infection, and this is thought to contribute to the poor antiviral immune response by CTLs." (PMID 35164678, 2022). "Numerous reports have highlighted the importance of circulating IL-10 levels in the course of HIV-1 infection." (PMID 34987508, 2021). "Previous studies demonstrated that let-7 miRNA family members target IL-10 mRNA, and that IL-10 inhibits cytotoxic T cell responses and contributes to T cell dysregulation during HIV-1 infection." (PMID 30702421, 2019).
HIV-1 infection (continued). "Because of the importance of TNF-α and IL-10 cytokines in the immuno-pathology of HIV-1 infection, several studies have focused on understanding the signaling pathways and the receptors engaged by gp120 R5-tropic on both permissive and non-permissive cells." (PMID 30464243, 2018). "It remains therefore to determine the molecular mechanisms involved in IL-10 production during the course of HIV-1 infection." (PMID 30464243, 2018). "Inhibitory cytokine IL-10 contributes to dysregulated cytotoxic T cell function to HIV-1 infection, and IL-10 was verified to be the target gene of let-7, which was down-regulated in CPs, compared with UCs." (PMID 28222782, 2017). "During chronic HIV-1 infection there was an increase of IL-10, TNF- α, IL-2, IL-6, IL-13 and IL-22 levels when compared to the control group." (PMID 27356504, 2016). "Consistent with their ability to activate STAT3, IL-6 and IL-10 also induced miR-29 and suppressed HIV-1 infection in HLACs." (PMID 26108174, 2015). "In this study, we found IL-10-producing B cell frequencies elevated in peripheral blood and sigmoid colon of untreated HIV-1 infection." (PMID 24586620, 2014). "In humans, lack of a clear correlation of IL-10 plasma levels with viral load in specific phases of HIV-1 infection as well as IL-10 fluctuations observed even in healthy subjects make it difficult to rely on plasma IL-10 as a biomarker for HIV-1 pathogenesis." (PMID 24695530, 2014). "In fact, even though IL-10 is elevated in plasma during chronic HIV-1 infection, with levels that correlate with HIV-1 viral load, higher levels of IL-10 expression were also associated with significantly higher plasma viral loads in acute infection." (PMID 24695530, 2014). "Our findings show that IL-10-producing B cells are induced early in HIV-1 infection, can be HIV-1 specific, and are able to inhibit effective anti-HIV-1 T cell responses." (PMID 24586620, 2014). "Taken together, these results indicate that IL-10-producing B cell frequencies are elevated in untreated viremic HIV-1 infection." (PMID 24586620, 2014). "Compared to uninfected controls, IL-10-producing B cell frequencies were elevated in both blood and sigmoid colon during the early and chronic phase of untreated HIV-1 infection." (PMID 24586620, 2014). "Ex vivo IL-10-producing B cell frequency in early HIV-1 infection directly correlated with viral load." (PMID 24586620, 2014). "We measured the levels of interferon (IFN)-γ and interleukin (IL)-10, since in vivo their plasma levels are altered at the earliest point of HIV-1 infection." (PMID 24086341, 2013). "Animal models suggest that IL-10 plays a significant role in viral persistence in general and has specific effects on HIV-1 infection through T-cell activity." (PMID 20976276, 2010). "Thus, reports from association studies like the present one on the IL10 gene family as well as other genes and their related families should be weighed in the context of what is known about the biologic pathways that influence the pathogenesis of HIV-1 infection." (PMID 20976276, 2010). "Further, several studies indicate that IL-10 production is induced in vivo and in vitro during HIV-1 infection." (PMID 20976276, 2010). "Cytokines encoded by the interleukin-10 gene (IL10) family have broad immunomodulatory function in viral persistence, and several SNPs in the IL10 promoter sequence have been reported to influence pathogenesis or acquisition of HIV-1 infection." (PMID 20976276, 2010). "Immune dysregulation in HIV-1 infection is associated with increased expression of inhibitory molecules such as CTLA-4, TGF-β, and IL-10." (PMID 20016783, 2009). "HIV-1 infection is accompanied by dysregulation of cytokine production in vivo and in vitro, with downregulation of interleukin (IL)-2 and interferons and upregulation of proinflammatory cytokines IL-1, IL-4, IL-6, IL-10, and TNFα." (PMID 38280430, 2024).
HIV-1 infection (continued). "HIV-1-infected HUT78 cells showed lower let-7 levels, accompanied by increased IL-10 levels, suggesting that the decreased let-7 level may be involved in the increased IL-10 expression seen in HIV-1 infection." (PMID 36142450, 2022). "HIV-1 infected HUT78 cells showed lower let-7 levels accompanied by increased IL-10 levels, suggesting that the decreased let-7 level may be involved in the increased IL-10 expression that was seen in HIV-1 infection." (PMID 35164678, 2022). "Direct evidence of this was observed in CSF during acute HIV-1 infection in our study through elevated pro-inflammatory chemoattractants IL-10, IP-10, neopterin, and sCD163, consistent with prior reports, and correlation between IP-10 concentration and activated CD4+ and CD8+ T cells and monocytes." (PMID 34874976, 2021). "Finally, the depletion of Siglec-1 abrogated the exacerbation of HIV-1 infection and production induced by TB in M(IL-10) macrophages." (PMID 32223897, 2020). "For example, IL-10 is produced constitutively during HIV-1 infection, and is considered as an important pathway by which HIV may induce immunodeficiency." (PMID 29874812, 2018). "Given the role of IL-10-producing Bregs in microbial persistence and a previous report that IL-10 mRNA transcript was upregulated in peripheral blood B cells in HIV-1 infected individuals, we investigated the role of IL-10-producing B cells in HIV-1 infection as a potential immune evasion strategy." (PMID 24586620, 2014). "In this study, we examined the role of IL-10-producing B cells in HIV-1 infection." (PMID 24586620, 2014). "Thus, some translocated microbial products can directly induce B cells to differentiate into IL-10-producing B cells in untreated HIV-1 infection via TLR-2 and/or TLR-9 signaling pathway." (PMID 24586620, 2014). "Since early HIV-1 infection is associated with dramatic CD8+ T cell activation and expansion, it is possible that IL-10-producing B cells play a physiologic role in preventing CTLs from killing B cells that are maturing to mount neutralizing antibody responses." (PMID 24586620, 2014). "However, it is also possible that IL-10-producing B cells are induced as a reaction to extensive immune activation, so characteristic of HIV-1 infection." (PMID 24586620, 2014). "Whether TIM-1 engagement is also important for IL-10-producing B cell differentiation in humans under physiological and pathological conditions, including HIV-1 infection, needs further study." (PMID 24586620, 2014). "Collectively, our data showed for the first time that, HIV-1 Tat interacts physically with high affinity with TLR4-MD2 to promote proinflammatory cytokines (TNF-α) and the immunosuppressive cytokine IL-10 both involved in immune dysregulation during early HIV-1 infection and AIDS progression." (PMID 24165011, 2013). "One way in which IL-27 may play a role in HIV-1 pathogenesis is in the increased levels of IL-10 noted in HIV-1 infection." (PMID 23527130, 2013). "Since interruption of the effects of this immunosuppressive cytokine is beneficial for HIV-1 control, higher levels of IL-10 secretion in response to Ad5 stimulation may present a barrier to controlling of HIV-1 infection with Ad5-vaccine-induced T cells." (PMID 21533229, 2011). "In light of these interactions, an IL-10/IL-10-receptor blockade has been suggested as a potential adjunctive therapy for HIV-1 infection, with a proposed mechanism of viral clearance in the production and maintenance of functional antigen-specific memory T cells." (PMID 21533229, 2011). "IL-10-positive CD8+ T cells have a regulatory role in the immune dysfunction of HIV-1 infection." (PMID 20976276, 2010). "Third, involvement of the IL-10 product in immunity to HIV-1 infection could be modulated through more complex interactions among related genes that may not be physically close but occur within the same biological system." (PMID 20976276, 2010).
HIV-1 infection (continued). "Treatment of B cells from healthy donors with microbial metabolites and Toll-like receptor (TLR) agonists could induce an IL-10 producing phenotype, suggesting that the elevated bacterial translocation characteristic of HIV-1 infection may promote IL-10-producing B cell development." (PMID 24586620, 2014). "Thus, IL-10-producing B cells in HIV-1 infection are enriched for HIV-1 trimeric Env specificity." (PMID 24586620, 2014). "Since TLR agonists in blood and tissues are elevated in untreated HIV-1/SIV infection due to microbial translocation, we hypothesized that the increased level of IL-10-producing B cells in untreated HIV-1 infection could be induced by translocated TLR agonists." (PMID 24586620, 2014). "Thus, our findings suggest the elevation of IL-10-producing B cells in untreated HIV-1 infection may be induced, at least in part, by microbial translocation in the gut." (PMID 24586620, 2014). "Here, we hypothesize that involvement of the IL-10 molecule in HIV-1 infection and pathogenesis could be modulated through complex interactions among IL10 and its related genes, especially those (IL19, IL20 and IL24) in the flanking genomic region and the IL-10 receptor genes (IL10RA and IL10RB)." (PMID 20976276, 2010). "As we described and observed before and herein, cmMTB-treated cells were positive for the M(IL-10) markers (CD16+CD163+MerTK+ and phosphorylated STAT3), and displayed a high rate of HIV-1 infection, as compared to those treated with cmCTR." (PMID 32223897, 2020). "Concentrations of IL-10, IL-4 and TNF-α were increased in the acute HIV-1 infection when compared to the control group." (PMID 27356504, 2016). "IL-10-producing B cells in HIV-1 infection are enriched for B cells that are specific for HIV-1 Env, and gp140-specific B cells were enriched in IL-10-producing B cells." (PMID 24586620, 2014). "All these cytokines, either because of their action to chronically stimulate the immune system, or because of their immunosuppressive action mediated by IL-10 and IDO are produced during HIV-1 infection." (PMID 24073214, 2013). "Accordingly, IL-10 and TGF-β have been reported to decrease phagocytic function in macrophages, and HIV-1 infection has been reported to inhibit complement receptor-mediated entry." (PMID 22412921, 2012). "Genotypes of IL10 and the evolutionarily conserved regulatory regions encoded by the related gene sequences could become useful biomarkers if their relationships to HIV-1 infection and disease progression with our without treatment are unambiguously established." (PMID 20976276, 2010). "In conclusion, HIV-1 infection shifts the cytokine profile from T-helper type 1 (TH1) towards T-helper type 2 (TH2), resulting in the excessive secretion of distinct cytokines, such as interleukin 4 (IL-4) and interleukin 10 (IL-10)." (PMID 37292193, 2023). "Also, they found reduced let-7 levels in primary CD4+ T cells retrieved from blood samples of subjects with HIV-1 infection, compared with non-infected controls, suggesting that the altered miRNA levels could be linked to the increased IL-10 expression in HIV patients." (PMID 35164678, 2022). "During such phase, uncontrolled replication of HIV-1 infection leads to activations of the CD8+ T lymphocytes (which can inhibit HIV replication by cytolytic and noncytolytic responses) and increases the concentration of cytokines such as IFN-γ and IL-10." (PMID 30057918, 2018). "Association of increased frequency of IL-10 detection in endocervical secretions of women with non-ulcerative STDs, like C. trachomatis have suggested that this may be a potential mechanism through which these infections may alter susceptibility to HIV-1 infection." (PMID 18828896, 2008). "This could be explained by the fact that IL-10 induces the autocrine production of IFN-I to indirectly modulate Siglec-1 expression in M(IL-10) macrophages, which then contributes to the exacerbation of HIV-1 infection as we previously reported." (PMID 32223897, 2020).
HIV-1 infection (continued). "Alternatively, polyclonal bystander activation of non-specific and low affinity B cells by cytokines and growth factors (e.g. IFN-a, TNF-a, IL-4, IL-10, BAFF) and surface CD40L, which may be over-expressed in untreated HIV-1 infection, may also affect the selection process." (PMID 24409278, 2014). "Not surprisingly, HIV-1 infection alters the PKC phosphorylation pathway to stimulate TNF-α production by monocytes as well as other cytokines and growth factors such as IL-6, IL-10, and MCP-1." (PMID 20604950, 2010).